RACGAP1 (Rac GTPase activating protein 1)
Diseases named in the same sentence as RACGAP1 in open-access papers (continued):
Sharing a sentence is not in itself a finding about the gene and the disease.
breast carcinoma (continued). "Three important proliferation genes for breast cancer are RACGAP1, TOP2A and Ki67." (PMID 27695115, 2016). "However, the exact roles of RACGAP1 in breast cancer, particularly in TNBC is largely unclear." (PMID 41444950, 2025). "Also, high expression of RACGAP1 is supposed to be not only a strong poor prognostic marker in luminal-like breast cancer but might also be a predictor of response to treatment with tamoxifen and adjuvant chemotherapy." (PMID 36313438, 2022). "In addition, increasing evidence reveals that RACGAP1 contributes to tumorigenesis and malignant progression of several malignancies, such as hepatocellular carcinoma 6, bladder cancer 7, gastric cancer 8, and breast cancer." (PMID 34239347, 2021). "Notably, RACGAP1P co‐expressed with RACGAP1 in breast cancer." (PMID 33252198, 2021). "RACGAP1 encodes a GTPase-activating protein (GAP), binds activated forms of Rho GTPases and stimulates GTP hydrolysis, which results in negative regulation of Rho-mediated signals, promoting malignant progression in gastric cancer, breast cancer and epithelial ovarian cancer." (PMID 33952272, 2021). "Some studies have reported the role of CCNB1, CCNB2, PTTG1, RACGAP1, and UBE2C in cell cycle regulation, aggressive tumor behavior, a poor prognosis, resistance to therapy, and cancer stem cell regulation in breast cancer." (PMID 41009526, 2025). "A cancer dependency map (depmap.org) further highlighted KIF11, AURKB, RACGAP1 and TPX2 as genes with essential effects in 47 breast cancer cell lines." (PMID 37835564, 2023). "Analysis results from the second server showed that the expression of RACGAP1 negatively influenced OS, distant metastasis-free survival (DMFS), and relapse-free survival (RFS) (p < 0.001) in breast cancer patients." (PMID 36430577, 2022). "We found that the expression levels of RACGAP1 and KPNA2 in breast cancer cells were positively relevant to cell cycle and proliferation through CancerSEA database." (PMID 36200070, 2022). "The novel prognostic SLEscore with five key therapeutic targets (RACGAP1, HMMR, TTK, TOP2A, and KIF15) was developed for the management of breast cancer patients with SLE using the LASSO algorithm." (PMID 36726984, 2022). "In a follow up study, authors used breast cancer models to investigate the role of lncRNA, RACGAP1P, which acts as an endogenous competitor for a microRNA that degrades RACGAP1." (PMID 35356277, 2022). "For validation in UALCAN, GEPIA, and KM, 5 core genes (KIF4A, RACGAP1, CKS2, SHCBP1, and HMMR) were found to highly expressed in breast cancer tissues with poor prognosis." (PMID 33959662, 2021). "As with our RACGAP1 finding, we determined significantly higher differential mRNA expression of EF2F1 in LumB versus LumA breast cancers via edgeR analysis (FDR = 2.59 × 10−27; logFC = −1.34)." (PMID 34179840, 2021). "Studies have shown that a two-gene ratio (HOXB13:IL17BR) and a five-gene (BUB1B, CENPA, NEK2, RACGAP1, RRM2) molecular grade index (MGI) are predictive of clinical outcomes among early-stage breast cancer patients." (PMID 23497539, 2013). "The linkages of RACGAP1 with ferroptosis had not been reported yet, and therefore, RACGAP1 was selected as a target gene to investigate its roles in ferroptosis in breast cancer." (PMID 41444950, 2025). "RACGAP1 is found to be upregulated and highly related to the clinical TNM stages of breast cancer." (PMID 39858398, 2024). "Furthermore, they showed that RACGAP1 improved mitochondrial fission via targeting ECT2 during anaphase and activating the ERK-DRP1 pathway, which promoted the metastatic progression of breast cancer." (PMID 36192752, 2022). "The results implied that RACGAP1 and KPNA2 might be a promising target in breast cancer therapy in the future." (PMID 36200070, 2022). "In breast cancer cells, RACGAP1P could competitively bind to miR‐345‐5p, which targets RACGAP1, and therefore up‐regulate RACGAP1." (PMID 33252198, 2021).
breast carcinoma (continued). "These five genes (KIF4A, RACGAP1, CKS2, SHCBP1, and HMMR) could be potential targets for therapy in breast cancer and prediction of prognosis on the basis of bioinformatical analysis." (PMID 33959662, 2021). "First, although high expressions of KIF4A, RACGAP1, CKS2, SHCBP1, and HMMR were independent prognostic factors of poor OS of breast cancer, all the data in our research came from online database and we need further experiments in vitro and in vivo to validate our findings." (PMID 33959662, 2021). "CKS2, KIF4A, RACGAP1, and SHCBP1 all have positive correlation with HMMR; they may become combined indicator of prognosis or targets for different subtypes of breast cancer." (PMID 33959662, 2021). "To validate whether RACGAP1 regulated FA metabolism by targeting CPT1A, we successfully overexpressed CPT1A in breast cancer cells transfecting with sh-RACGAP1, and its overexpression exhibited no influences on the expression of RACGAP1." (PMID 41444950, 2025). "Additionally, their expression was positively correlated with that of Ki-67, PCNA and MCM2, which was consistent with the predictions of CancerSEA, implying that RACGAP1 and KPNA2 could facilitate breast cancer progression." (PMID 36200070, 2022). "Our data from cell cycle analysis and real-time PCR suggested that AS extract exerted mild stimulatory activities in breast cancer cells at S phase; however, it did not up-regulate the tested proliferation-related genes, TOP2A and RacGAP1, as well as survival-related gene, survivin." (PMID 31293425, 2019).
hepatocellular carcinoma (26 papers, 2016 to 2025). A malignant tumor that arises from hepatocytes. "Similarly, hsa_circ_0088364 and hsa_circ_0090049, which are upregulated in hepatocellular carcinoma, are associated with the upregulation of RACGAP1 at the mRNA level." (PMID 39858398, 2024). "Considering hepatocellular carcinoma, RACGAP1 upregulation was significantly associated with the early recurrence of human hepatocellular carcinoma, as it activates the RACGAP1/Rho/ERK signaling axis as a competing endogenous RNA to promote early recurrence of hepatocellular carcinoma." (PMID 36430577, 2022). "In addition, TCGA database analyses showed that high expression of RACGAP1 was closely associated with poor prognosis (3-year overall survival) of several cancers, e.g., kidney renal papillary cell carcinoma, hepatocellular carcinoma, lung adenocarcinoma, sarcoma and skin cutaneous melanoma." (PMID 30866526, 2019). "RacGAP1 is essential for cell survival and proliferation across diverse cell types, such as hepatocellular carcinoma cells, uterine carcinosarcoma cells, pseudostratified epithelial cells and hematopoietic cells." (PMID 41230850, 2025). "In the digestive system, RACGAP1 is overexpressed in both the digestive tract and digestive glands, especially in hepatocellular carcinoma (HCC) for digestive glands." (PMID 39858398, 2024). "In hepatocellular carcinoma, it has been shown that RACGAP1 has an inhibitory effect on the Hippo signaling pathway to promote the development of cancer." (PMID 39858398, 2024). "In hepatocellular carcinoma, RACGAP1 promotes cell proliferation and cytokinesis in coordination with Hippo pathway through increasing activity of RhoA and polymerization of filamentous actin." (PMID 38898473, 2024). "RACGAP1P, as a competitive endogenous RNA (ceRNA), is reported to be upregulated in hepatocellular carcinoma, resulting in the activation of the RACGAP1/RhoA/ERK pathway by the inhibition of miR-15-5p interference on RACGAP1 expression." (PMID 39858398, 2024). "Knockdown of RACGAP1 suppressed proliferation, invasion and migration of hepatoma cells in our preliminary study." (PMID 35958019, 2022). "Our study also demonstrated that knockdown of RACGAP1 reduced the proliferation of hepatoma cells by CCK-8 assay and colony formation." (PMID 35958019, 2022). "To explore the underlying function of RACGAP1 in vitro, we chose Huh7 and HCCLM3 for knockdown and SMMC7721 for overexpression according to the result in RT-PCR of hepatoma cells." (PMID 35958019, 2022). "Upregulated RACGAP1 predicted the poor outcomes in patients with hepatocellular carcinoma, ovarian cancer, and bladder cancer." (PMID 32149105, 2020). "Knocking out RACGAP1 in hepatocellular carcinoma cells hampered cytokinesis and induced cell apoptosis." (PMID 32149105, 2020). "RACGAP1 has been widely reported to take part in the pathogenesis of various cancers, such as colorectal cancer, hepatocellular carcinoma, and others, but its role in the development of PCa was also unclear." (PMID 31306099, 2019). "For instance, Signal transducer and activator of transcription 3 (STAT3) is a transcriptional factor which has been reported to activate the transcription of RacGAP1 in hepatocellular carcinoma cells." (PMID 31426369, 2019). "Previous studies have demonstrated that aberrant expression of RacGAP1 occurs in different cancer types, including cervical cancer, esophageal cancer, glioma, ovarian cancer, colorectal cancer, gastric cancer and hepatocellular carcinoma." (PMID 40497948, 2025). "RACGAP1P, a pseudogene, was reported to be upregulated in hepatocellular carcinoma, leading to the overexpression of RACGAP1 by competitively binding with miR-15-5p, the latter of which could inhibit RACGAP1 expression." (PMID 39858398, 2024). "Moreover, in hepatocellular carcinoma, it is indicated that RACGAP1 can activate RhoA to function, and it was verified that RACGAP1 enhances the stability of ECT2 to improve ECT2-mediated RhoA activation." (PMID 39858398, 2024).
hepatocellular carcinoma (continued). "Importantly, the oncogenic roles of RACGAP1 have been demonstrated in uterine carcinosarcoma, gastric cancer, and hepatocellular carcinoma." (PMID 36471446, 2022). "RACGAP1 was found to facilitate hepatoma cell proliferation and invasion both in vivo and vitro." (PMID 35958019, 2022). "Furthermore, the positions S257, T338, and T580 of RACGAP1 were significantly phosphorylated in tissues of hepatocellular carcinoma, LUAD, and ovarian cancer relative to healthy tissue." (PMID 36430577, 2022). "In addition, it has been reported that siRNA-mediated knockdown of RACGAP1 in human hepatoma cell lines inhibits the replication of HCV RNA." (PMID 33539396, 2021). "Recent studies reported overexpression of RACGAP1 in several types of cancers (e.g., gastric cancer, colorectal cancer, uterine carcinosarcoma, hepatocellular carcinoma and epithelial ovarian cancer), and its aberrant expression was associated with poor prognosis in patients with these cancers." (PMID 30866526, 2019). "In hepatocellular carcinoma (HCC), RacGAP1 supports tumor growth by suppressing the Hippo/YAP pathway." (PMID 40497948, 2025). "RACGAP1 is a suppressor gene in hepatocellular carcinoma (HCC), and its expression can predict early HCC recurrence." (PMID 38903532, 2024). "ECT2 facilitates early recurrence and metastasis of hepatocellular carcinoma through activation of the Rho/ERK signaling axis and interaction with RACGAP1." (PMID 39100078, 2024). "In the Hippo pathway, RACGAP1 showed colocalization with the translocated promoter region (TPR) and aurora kinase B during cytokinesis in hepatocellular carcinoma." (PMID 39858398, 2024). "The transcription of RACGAP1 is also upregulated by YY1 in glioma, Recombinant GA-Binding Protein Transcription Factor Alpha (GABPA) in hepatocellular carcinoma, FOXM1 in cervical cancer and rbp-Jkappa in prostate cancers." (PMID 39858398, 2024). "In this study, we proved that RACGAP1 was over-expression both in HCC tissues and hepatoma cell lines." (PMID 35958019, 2022). "RACGAP1, TOP2A and some other genes co-expressed to regulate the immunity response in hepatocellular carcinoma." (PMID 33193623, 2020). "In hepatocellular carcinoma, ECT2 enhances the expression and stability of RACGAP1 and accelerates activation of the ECT2-mediated Rho/ERK signaling axis to promote tumor metastasis." (PMID 31334127, 2019). "Again, the trend of elevated RACGAP1 expression in tumor tissues was observed in colon cancer, HNCS, LUAD, PAAD, UCEC, ovarian cancer, and hepatocellular carcinoma, where IHC staining, which was high for RACGAP1 in analyzed tumor tissues, confirmed our findings." (PMID 36430577, 2022).
colorectal cancer (18 papers, 2016 to 2025). A primary or metastatic malignant neoplasm that affects the colon or rectum. "It is also revealed that RACGAP1 expression is associated with malignant biological behaviors of colorectal cancer cells and with the progression of colorectal cancer into a poorer T stage, invasion and lymph node metastasis, as well as recurrence." (PMID 39858398, 2024). "Increased expression of RACGAP1 protein has been previously associated with poor survival as well as significantly associated with increased tumour malignancy in colorectal cancer." (PMID 35933325, 2022). "Colorectal cancer patients have poor prognoses linked to RACGAP1 expression." (PMID 40421085, 2025). "For this purpose, the current study analyzed multiple databases, with our results showing that RACGAP1 mRNA expression was upregulated in multiple tumor tissues (including lung, liver, and colorectal cancers among others) compared to normal adjacent tissues." (PMID 38622149, 2024). "RACGAP1 can increase the potential for malignancy and can be used as a biomarker for lymph node metastasis and prognosis in colorectal cancer." (PMID 38468345, 2024). "Contrary to these data in gastric cancer, there was a recent report on upregulation of RACGAP1 in colorectal cancer with RACGAP1 being an independent predictive factor for prognosis." (PMID 26778597, 2016). "Moreover, recent findings suggest the potential involvement of RacGAP1 in the regulation of the Wnt pathway in colorectal cancer and gastric cancer." (PMID 40497948, 2025). "In colorectal cancer, hsa_circ_0001955, hsa_circ_0071681 and hsa_circ_000240 could affect survival via RACGAP1 regulation." (PMID 39858398, 2024). "In addition, a recent study suggested that patients with high nuclear RACGAP1 expression in colorectal cancer have worse prognosis compared to the high cytoplasmic expression of RACGAP1." (PMID 38898473, 2024). "Furthermore, RACGAP1 expression was found to increase malignant tumor potential and was used as a predictive biomarker for lymph node metastasis and poor prognosis in colorectal cancer." (PMID 36430577, 2022). "Notably, in ovarian and colorectal cancer the expression of RacGAP1 positively correlated with lymph node metastasis and poor survival, respectively." (PMID 34493786, 2021).
gastric cancer (16 papers, 2016 to 2025). A primary or metastatic malignant neoplasm involving the stomach. "In conclusion, this is, to our knowledge, the first study showing an association of AURKA and RACGAP1 in gastric cancer as well as a connection with Wnt‐signaling components." (PMID 26778597, 2016). "RACGAP1 has been identified as a hub gene and significantly associated with overall survival in patients with various cancer types, such as pancreatic ductal adenocarcinoma, gastric cancer, cervical cancer and lung adenocarcinoma." (PMID 34336648, 2021). "The development of gastric cancer involves RACGAP1 in the interference of stemness properties, enabling RACGAP1 to be a possible treatment target for gastric cancer." (PMID 39858398, 2024). "By using immunohistochemistry, it was indicated that, at the invasive front, RACGAP1 expression correlates with the exacerbation of gastric cancer." (PMID 39858398, 2024). "Gastric cancer cell proliferation, migration, and invasion were all enhanced when RACGAP1 was overexpressed." (PMID 39403142, 2024). "Intriguingly, it is notable that RACGAP1 expresses at a lower level in gastric cancers than in normal tissues, which is inconsistent with most other studies." (PMID 39858398, 2024). "One study reported that RACGAP1 exhibited a low expression level in gastric cancers, thereby reducing the inactivation of Rho-GTPases, which is in contrast to other studies about gastric cancers." (PMID 39858398, 2024). "For GIT-related cancers, there was a significant correlation of RACGAP1 protein expression at the invasive front of gastric cancer with older age, tumor size, lymph node metastasis, lymphatic invasion, vascular invasion, and advanced stage." (PMID 36430577, 2022). "RACGAP1 expression was significantly correlated with vascular invasion and advanced stage in gastric cancer." (PMID 35197055, 2022). "Gastric cancer was also affected by RACGAP1 expression in terms of patients’ survival in relation to OS, PPS (p < 0.001), and F.P. (p < 0.01)." (PMID 36430577, 2022). "The lower expression in gastric cancer samples compared to controls in our gastric cancer cohort is in line with the downregulation of RACGAP1 that was predicted by the computational analysis." (PMID 26778597, 2016). "Immunohistochemistry confirmed expression of the RACGAP1 protein in gastric cancer and the tumor‐adjacent mucosa." (PMID 26778597, 2016). "This is the first evidence of a direct link of AURKA and Wnt signaling via RACGAP1 in gastric cancer." (PMID 26778597, 2016). "Interestingly, a possible functional link between RacGAP1 and the Wnt/β-catenin signaling pathway has been suggested in nasopharyngeal carcinoma, as well as colorectal and gastric cancers." (PMID 40497948, 2025). "There was a significant amount of RACGAP1 found in the cells of stomach cancer." (PMID 39403142, 2024). "A strong and unexpected association emerged between AURKA and the Wnt modulator Rac GTPase‐activating protein 1 (RACGAP1) in a phenotype‐specific gastric cancer signaling network, that we validated by quantitative RT‐PCR in an independent, prospective cohort of gastric cancer patients." (PMID 26778597, 2016). "Contradictorily, it was also reported that RACGAP1 in gastric cancer could inactivate Rac and RhoA." (PMID 39858398, 2024). "Another study showed a direct positive correlation between RACGAP1 and AURKA in gastric cancer and that AURKA is also an important neuroendocrine (NE) marker of PCa." (PMID 37196108, 2023). "There is a direct positive correlation between RACGAP1 and AURKA in gastric cancer, and STAT3 and AURKA are all closely related to the neuroendocrine transformation of PCa." (PMID 37196108, 2023). "Helicobacter pylori infection status had no influence on RACGAP1 staining in patients with gastric cancer (P = 0.104)." (PMID 26778597, 2016). "Differential expression analysis revealed a significant downregulation of both AURKA and RACGAP1 in gastric cancer compared to noncancer controls." (PMID 26778597, 2016).
gastric cancer (continued). "Gene expression of RACGAP1 in gastric cancer samples was significantly lower than in noncancer control biopsies (P < 0.001)." (PMID 26778597, 2016). "There might be a possible field effect on the noncancerous gastric mucosa at the stage of advanced gastric cancer, especially with regard to the role of RACGAP1 regulating invasion and proliferation." (PMID 26778597, 2016).